AHR (aryl hydrocarbon receptor)
Diseases named in the same sentence as AHR in open-access papers (continued):
Sharing a sentence is not in itself a finding about the gene and the disease.
colitis (continued). "1,4-dihydroxy-2-naphthoic acid (DHNA) is a probiotic AhR activator that has been shown to induce antimicrobial protein production, alter microbiota composition, and inhibit DSS-induced colitis in mice." (PMID 35626744, 2022). "While AHR and its target gene CYP1A1 were increased after L-fucose administration in DSS-induced colitis." (PMID 36432480, 2022). "Similar protective effects against LPS-induced colitis were also observed; IPA protects LPS-induced mice by activating AhR to promote IL-10 production while suppressing the gene expression of TNF-α." (PMID 36159803, 2022). "Previous reports have indicated that AhR controls glucose metabolism and norisoboldine, a natural AhR agonist, was found to promote Treg differentiation and disease remission in DSS-induced colitis by repressing glycolysis." (PMID 36131123, 2022). "In an experimentally-induced colitis model using germ free Il-10−/− mice, GUT-108 colonization helped correct dysbiosis via modulation of AhR pathway genes." (PMID 35626744, 2022). "Similarly, specific ablation of AhR signaling in mucosal dendritic cells (DCs) impairs epithelial morphogenesis (with reduced Paneth cell differentiation and increased goblet cell differentiation) as well as barrier function, resulting in the exacerbation of inflammation in experimental colitis." (PMID 36144238, 2022). "Previously, it was shown that AhR promotes T reg expansion in the gut, but the role of AhR-CYP1A1-promoted T regs with respect to the control of colitis is not clearly understood." (PMID 36159798, 2022). "Activation of AhR in a humanized murine model of IBD, whereby human CD4+ T cells induce colitis upon exposure to TNBS, reduced the inflammatory response by inducing Treg cells and favoring oral immune tolerance." (PMID 33562721, 2021). "Our results are consistent with previous studies showing that Ficz treatment alleviated colitis, EAE and celiac disease, leading to AhR activation regulating the host immunity in inflammatory and metabolic diseases." (PMID 34297785, 2021). "AhR activating strains of Lactobacillus and AhR agonists were found to ameliorate the DSS-induced colitis in these knockouts." (PMID 34747326, 2021). "Strains of Lactobacillus, with AhR activating properties, reduced the severity of DSS-induced colitis in mice." (PMID 33562721, 2021). "Administration of B-naphtoflavone, an AhR agonist, improved DSS-induced colitis in mice and downregulated colitis-induced pro-inflammatory cytokines such as TNFα, IL6 and IL1β mRNA." (PMID 32957545, 2020). "We used AhR agonist TCDD, CH223191 to verify that the effects of baicalein on the treatment of colitis mice are an AhR-dependent manner." (PMID 33082710, 2020). "The positive results of AhR activation in colitis models and recent clinical studies of curcumin in the management of IBD illustrate the great potential of nutritional modification of AhR signaling." (PMID 32957545, 2020). "IL-21 also promotes IL-22 expression in mucosal T-cells through a mechanism involving STAT3, retinoid-related orphan receptor γt, and aryl hydrocarbon receptor, thereby helping protect immunodeficient mice from DSS colitis." (PMID 32855621, 2020). "Promisingly there are successful therapeutic agents determined to be AhR agonists that treat TNBS- and DSS-induced colitis via the NLRP3 inflammasome but they are still far from many." (PMID 32456012, 2020). "TCDD-activated AhR displays to partially demethylate CpG islands of FOXP3 and to hypermethylate IL-17 promoters in colitis." (PMID 32899152, 2020). "AhR activation by ligand administration and AhR knock-down in mouse suppressed and enhanced DSS-induced colitis, respectively suggesting a beneficial effect of AhR activation in IBD17,18." (PMID 30679727, 2019). "AHR is down-regulated in intestinal tissue of patients with IBD; and AHR signaling via IL-22 inhibits inflammation and colitis in the gastrointestinal tract of mice." (PMID 31001262, 2019).
colitis (continued). "Quantitative RT-PCR showed that DHA significantly reduced expression levels of the transcription factors PU.1 (Th9) and AHR (Th22) and increased levels of Foxp3 (Treg) in the OXA colitis model." (PMID 31284478, 2019). "Previous studies have described a protective role for AhR, another established ARNT binding partner, in colitis." (PMID 30455703, 2018). "By contrast, treatment of AhR agonist 6-formylindolo(3, 2-b)carbazole (FICZ), a tryptophan derivative, reversed relapsing TNBS and DSS-induced colitis." (PMID 29910812, 2018). "Consistent with this, AHR is downregulated in the intestinal tissue of patients with IBD113 and AHR activation protects humanized mice against colitis by induction of regulatory T cells." (PMID 30120222, 2018). "In the current study, we used TCDD to activate the AhR and determine the reciprocal regulation of Th17 and Treg differentiation during DSS-induced colitis." (PMID 21858153, 2011). "AS-IV ameliorated colitis by downregulating IDO1 expression, while upregulating the expression of tryptophan hydroxylase 1 (TPH1), DDC, monoamine oxidase A (MAO-A), and the aryl hydrocarbon receptor (AhR), as well as inhibiting NF-κB p65 phosphorylation." (PMID 42195848, 2026). "However, microbiota from anti‐CD40+I3C treated mice significantly increased the expression of AhR and BD1 compared to cells cocultured with microbiota from colitis mice." (PMID 40410944, 2025). "In addition, the expression of AhR targeted genes (CYP1A1, IL-10, and IL-22) was enhanced in colon of colitis mice through treatment with pasteurized A. muciniphila or Amuc_1100." (PMID 41488633, 2025). "In colitis-associated CRC models, increased tumor formation was observed in mice lacking AhR, suggesting a potential tumor-suppressive role for AhR." (PMID 40771692, 2025). "After establishing an in vitro colitis model by stimulating Caco-2 cells with TNF-α, we investigated whether AHR could be modulated by its well-defined exogenous and endogenous ligands in this system." (PMID 41373818, 2025). "Experiments involving colitis in vivo in mice or in vitro colon organoid models were performed to determine how the expression of mucin 2 protein was altered with or without AHR in intestinal epithelial cells (IECs) in response to indole-3-carbinol." (PMID 40765830, 2025). "Conversely, colitis mice and IBD patients’ intestines may contain microorganisms that directly impact the production of α-defensin 1 through activation of AhR." (PMID 39894796, 2025). "Notably, AhR expression is markedly downregulated in inflamed tissues of patients with IBD and DSS-induced colitis mouse models, and the binding affinity of IAA for AhR is relatively low compared to that of other endogenous ligands." (PMID 41373425, 2025). "In this study, we investigated whether L. murinus, a putative probiotic strain, can influence AHR signaling and mitigate TNF-α-induced epithelial dysfunction in an in vitro colitis model." (PMID 41373818, 2025). "Mechanistically, isobutyrate can increase the relative abundance of Lactobacillus reuteri, thereby increasing the production of indole-3-lactic acid, regulating aryl hydrocarbon receptor expression and downstream signaling pathways, and regulating Foxp3+ CD4+ T cell recruitment to alleviate colitis." (PMID 40342298, 2025). "In both DSS-induced colitis mouse models and IL-10−/− spontaneous colitis mouse models, IPA enhances the integrity of the epithelial barrier and alleviates colitis by activating the AHR signaling pathway." (PMID 41155173, 2025). "Similarly, mulberry bark-derived EVs (MBELN) activate the aryl hydrocarbon receptor (AhR) signaling pathway through HSPA8, alleviating colitis in mouse models." (PMID 41358005, 2025). "They found that the TRP diet improved colitis symptoms and severity in wild-type mice but not in AhR gene knockout mice." (PMID 38167867, 2024).
colitis (continued). "In summation, AhRΔRorc colitis mice treated with I3C mirrored LM and AhRΔRorc disease controls in both sexes, if not with slightly more severe colitis phenotype, highlighting the importance of AhR in these cell types when responding I3C administration." (PMID 39229279, 2024). "The indispensability of AhR/Nrf2 signaling was further validated, showing that UroA/UAS03 activation did not induce expression of gut epithelial tight junction proteins and protect from experimentally-induced colitis in AhR- and Nrf2-KO mice." (PMID 39211042, 2024). "Dietary supplementation with an AhR pre-ligand, indole-3-carbinol, conferred protection against colitis while protection failed in mice lacking AhR in myeloid cells." (PMID 39113799, 2024). "Moreover, TCDD, which functions as an AHR agonist, can lessen the symptoms of 2,4,6-trinitrobenzene sulfonic acid (TNBS)-induced colitis." (PMID 38542367, 2024). "However, they found that pasteurized Akk supplementation increased serum levels of endogenous ligands of AhR derived from Trp metabolism (i.e., IAld, 5HIAA) in mice with DSS-induced colitis." (PMID 39517263, 2024). "Depletion of AhR in IECs also did not impact the ability of I3C to enhance the production of IL-22 by ILC3s during colitis." (PMID 38397081, 2024). "Similarly, oral administration of another AhR agonist, β-naphthoflavone, was shown to decrease the severity of DSS-induced colitis while reducing pro-inflammatory cytokines such as tumor necrosis factor -α (TNF-α), IL-6, and IL-1β." (PMID 39767818, 2024). "It was demonstrated that a few AHR agonists, including TCDD and FICZ, reduce colitis symptoms." (PMID 38542367, 2024). "Both cardamonin and norisoboldine (NOR) from Tilia can alleviate TNBS-induced colitis in mice by activating AHR and eventually inhibiting the activation of colonic NLRP3 inflammatory vesicles." (PMID 37179416, 2023). "Our findings show that AHR’s DNA-binding domain and ability to bind to AHREs are required to reduce inflammation, maintain a healthy intestinal environment, and protect against DSS-induced colitis." (PMID 36519841, 2023). "Oral administration of 1,4-dihydroxy-2-naphthoic acid (DHNA), an AHR activator derived from the cheese bacteria Propionibacterium freudenreichii ET-3, induced anti-microbial peptides in the intestine, further controlling inflammation in DSS-colitis." (PMID 37179416, 2023). "The AHR agonist β-naphthoflavone was administered orally and reduced DSS-induced colitis." (PMID 37179416, 2023). "AhR maintain intestinal permeability and ameliorating DSS-induced colitis." (PMID 36678175, 2023). "Similarly, in a recent study, it was demonstrated that herbicide propyzamide acted as an AhR antagonist and, together with TNBS (2,4,6-trinitrobenzene sulfonic acid, a chemical inductor of colitis in mice), boosted intestinal pathologies in zebrafish." (PMID 37958638, 2023). "AhR activation by FICZ relieved colonic inflammation, reduced IL-6 and claudin-2 expression, and kept intestinal barrier function in a mouse model of DSS-induced colitis." (PMID 36678175, 2023). "This suggests that AhR is involved in the synergistic effects of combined butyrate and VD3 on the invasiveness of Salmonella infection in colitis mice by enhancing antibacterial responses to defense against infection but reducing tight junction proteins expression to block invasiveness." (PMID 36678175, 2023). "Apart from the improved intestinal permeability, researchers have also found reduced colonic inflammation (e.g., IL-6, IL-1β, TNF-α) and overall disease activity index (DAI) after urolithin A therapy which active the AHR in 2, 4, 6trinitrobenzenesulphonic acid (TNBS)-induced colitis models." (PMID 37942478, 2023). "Mice lacking AHR had more severe colitis, whereas those treated with AHR agonists had attenuated disease progression." (PMID 37179416, 2023). "Here, we asked whether AhR downstream inducer, CYP1A1 is required for UroA-mediated functional activities to protect against colitis." (PMID 36159798, 2022).
colitis (continued). "Indeed, administration of L. bulgaricus OLL1181 to mice induced the expression of the AhR target gene Cyp1a1 and ameliorated DSS-induced colitis." (PMID 36144238, 2022). "In addition, decreased AhR signaling in ILC3s can alter the balance between ILC3 and ILC1 populations and promote the development of colitis." (PMID 35892593, 2022). "Administration of indole-3aldehyde (IAld) rescues wild-type mice from DSS-induced colitis but not the Ahr−/− mice, indicating the role of AhR in mucosal protection." (PMID 36076980, 2022). "While UroA has been shown to activate AhR and enhance gut barrier function, involvement of downstream AhR signaling pathways that are potentially responsible for anti-inflammatory, gut barrier protective and anti-colitis activities have not been investigated." (PMID 36159798, 2022). "Cell-specific deletion of AhR and CYP1A1 may provide better understanding of how UroA-mediated activities regulate differentially to mitigate colitis." (PMID 36159798, 2022). "Interestingly, after AhR activation by Ficz exposure, CD8αα+ TCRαβ+ intraepithelial lymphocytes (IELs) resist apoptosis with AhR, IL-15 and IL-10 up-regulation, and IFN-γ reduction in a colitis model." (PMID 34122415, 2021). "AhR maintain intestinal permeability, with Ficz promoting goblet cell differentiation through AhR-pErk1/2 signaling pathway, and ameliorating DSS-induced colitis." (PMID 34122415, 2021). "Furthermore, AhR agonist FICZ exerted protective effects in various disease models like metabolic syndrome, autoimmune uveitis, colitis, psoriasis, etc." (PMID 33280241, 2021). "Activation of AhR by a non-toxic flavonoid, β-naphthoflavone (βNF) was observed to reduce the severity of colitis in a murine model through inhibition of NF-κB pathway and pro-inflammatory cascade of cytokines." (PMID 34249001, 2021). "Reduced AhR expression has been seen in individuals with IBD, colitis, Crohn’s disease and CRC." (PMID 33916690, 2021). "Q- or I3C-induced amelioration of colitis is not observed in Ahr-/- mice suggesting the requirement of AhR ligation and signalling." (PMID 33668818, 2021). "It is a nontoxic AhR agonist that has been shown to act on both T cells and dendritic cells to suppress gut inflammation in colitis, as well as display anti-cancer activity in multiple cell types." (PMID 35008717, 2021). "In the T cell transfer colitis model, AhR activation ameliorates the course of colitis induced by wild-type T cells but does not influence colitis induced by Smad7 Tg T cells." (PMID 33920230, 2021). "I3A is a ligand for the mouse aryl hydrocarbon receptor (AHR) and was sufficient to induce the production of IL-22, leading to an improvement in intestinal barrier function and an enhanced resistance to DSS-induced colitis." (PMID 33255483, 2020). "The AhR/Nrf2 signals produced by cardamonin would then activate NQO1, which has inhibitory effects in NLRP3 inflammasome priming, which lead to a reduction in pro-inflammatory cytokines and produce anti-colitis effects." (PMID 32456012, 2020). "Since the levels of IPA in colonoscopy aspirates from 36 healthy and colitis subjects can approach ≈0.5 μM (unpublished observations, Mani Lab), the biological effects of IPA mediated by the AhR could be negligible." (PMID 32283770, 2020). "The protection via AhR had previously been described in several models of lung inflammation including the COPD model induced by cigarette smoke and idiopathic pneumonia syndrome or in the DSS-induced colitis model." (PMID 32161582, 2020). "In fact, AhR activation has been shown to promote mucosal healing and decrease intestinal inflammation in animal models of inflammatory bowel disease (IBD] including both DSS and TNBS-induced colitis." (PMID 32017483, 2020).
colitis (continued). "Boosting CD39 expression either by inducing AhR-signaling or by administering exogenous ADPase, which displays ectoenzymatic activity comparable to human CD39, showed important immunoregulatory effects in vitro and in vivo, in experimental colitis models." (PMID 33072065, 2020). "In contrast, UroA/UAS03 did not block LPS-induced IL-6 production in AhR−/− macrophages up to 30 μM as well as in AhR−/− mice in TNBS-induced colitis model suggesting that UroA/UAS03 mediate anti-inflammatory activities through AhR-dependent manner." (PMID 30626868, 2019). "In a T cell-transfer genetic mouse model of colitis, AhR-expressing Tregs exhibited increased suppressive activity compared with Tregs lacking AhR expression." (PMID 31772949, 2019). "As evidenced in a DSS-induced colitis model, IPA protects lipopolysaccharide (LPS)-challenged mice by activating AhR to promote interleukin-10 (IL-10, an anti-inflammatory cytokine) production while suppressing gene expression of TNF-α, a proinflammatory cytokine." (PMID 30691236, 2019). "In this context, we have shown that activation of AhR in intestinal mucosal cells stimulates the production of IL-22 and down-regulates the production of inflammatory cytokines, such as IFN-γ and TNF-α, thereby attenuating experimental colitis in mice." (PMID 30778350, 2019). "Moreover, DHA significantly decreased the protein expression levels of PU.1 (Spi-1 proto-oncogene) and AHR (Aryl hydrocarbon receptor) in the LPMCs of the OXA colitis model and decreased the protein levels of T-bet and RORγt in the TNBS colitis model." (PMID 31284478, 2019). "In AhR−/− mice, the endogenous ligands cannot act as bioregulatory molecules due to lack of AhR potentially leading to severe colitis phenotype compared to wild type mice." (PMID 30626868, 2019). "AhR plays a critical role in maintaining gut immune tolerance and barrier function, as evidenced by the finding that AhR-null mice exhibit severe symptoms and mortality in animal models of dextran sodium sulfate (DSS)-induced colitis." (PMID 30340338, 2018). "In the T-cell transfer colitis model, AhR activation significantly ameliorates the course of colitis driven by wild-type T cells, but does not influence colitis induced by Smad7 transgenic T cells." (PMID 29973939, 2018). "Then, the causal link between activation of AhR, reduction of glycolysis, regulation of NAD+/SIRT1/SUV39H1/H3K9me3 signals, induction of Treg cells, and alleviation of colitis by NOR was confirmed in mice with colitis." (PMID 29449535, 2018). "NOR, a natural AhR agonist, yielded excellent amelioration of colitis and accompanied with elevated percentages of Treg cells." (PMID 29449535, 2018). "Our findings suggest that myeloid AhR is not likely a major contributor to colitis resolution, as disruption of HIF-1α and HIF-2α signaling accounts for the majority of ARNT-dependent effects in our model." (PMID 30455703, 2018). "In addition, AhR activation by 6-formylindolo (3,2-b) carbazole (Ficz) down-regulates IL-7 and reduces inflammation in DSS-induced colitis." (PMID 26264025, 2015). "Moreover, several recent studies have shown that AhR activation leads to an improvement of DSS colitis, TNBS colitis and oxazolone colitis." (PMID 23638007, 2013). "Moreover, treatment of mice with an AhR antagonist reduced IL-22 production and enhanced the severity of TNBS-colitis." (PMID 22082127, 2011). "In TNBS-induced colitis in humanized mice, the nontoxic AHR agonist methyl 2-(1’H-indole-3’-carbonyl)-thiazole-4-carboxylate (ITE) induced functional human Tregs, which inhibited effector T-cell proliferation in vitro in a CD39- and granzyme B-dependent manner, leading to the up-regulation of IL-22." (PMID 41019044, 2025). "Thus, in mice that failed to express AhR in CECs, I3C failed to induce mBD‐1 and as a result, they developed severe colitis." (PMID 40410944, 2025).